ATG5 (autophagy related 5)
Diseases named in the same sentence as ATG5 in open-access papers (continued):
Sharing a sentence is not in itself a finding about the gene and the disease.
colon carcinoma (24 papers, 2012 to 2024). "Immunoblotting showed increased expression levels of cleaved PARP, cleaved caspase 3, and BiP in colon tumor tissues of Atg5-deficient mice compared with Ctr mice." (PMID 26496833, 2015). "Results showed that the deficiency of TNFR2 on MC38 and CT26 colon cancer cells markedly decreased p62/SQSTM1 expression while increased the expression of Beclin1, Atg5, and LC3-II/LC3-I." (PMID 36923938, 2023). "To examine the effect of TNFR2 deficiency on autophagy of mouse colon cancer, we analyzed the autophagy-related hallmarks including Beclin1, LC3, Atg5, and p62/SQSTM1 by Western Blotting." (PMID 36923938, 2023). "It was discovered that chloroquine and oxaliplatin interact synergistically on colon cancer cell lines, which confirmed the silencing of ATG5 through RNA interference, whereas the incubation of cells with beclin-1 resulted in the inhibition of autophagy." (PMID 33467015, 2021). "An example of this is the increased expression of ATG7 as well as down-regulation of ATG5 and beclin-1 during apoptosis of colon cancer cells." (PMID 33467015, 2021). "For example, the pharmacological inhibition of autophagy and the knockdown of Atg-5 or Atg-7 in human colon cancer cell lines have been shown to increase proteasomal activity." (PMID 32784405, 2020). "Knockdown of Atg5 or Atg7 significantly reduced the cytotoxic effect of FK-16, suggesting that FK-16 induced autophagic cell death in colon cancer cells." (PMID 23700428, 2013). "Similarly, in two lines of primary colon cancer cells (patient-derived), icaritin (10 μM) treatment induced Beclin-1, ATG-5 and LC3B-II upregulation but p62 degradation." (PMID 28103582, 2017). "In contrast, the colon tumors of the Atg5-deficient mice exhibited partial negative staining for PCNA and Ki67." (PMID 26496833, 2015). "To investigate the involvement of autophagy in colon cancer in vivo, we treated mice mutant for Atg5, an indispensable gene for autophagy, with azoxymethane/dextran sodium sulfate (AOM/DSS), which is an established animal model used to induce and analyze colon cancer." (PMID 26496833, 2015). "Next, we examined the distribution of CK19 and Atg5 in AOM/DSS-derived colon tumors." (PMID 26496833, 2015). "Next, we suppressed Atg5 gene expression in established colon tumors." (PMID 26496833, 2015). "To determine whether RACK1-induced autophagy promotes colon cancer cell proliferation and inhibits colon cancer cell apoptosis, we used siRNA against ATG5 or BECN1 to inhibit autophagy in the RACK1 OE colon cancer cells, and analyzed the changes of cells proliferation and apoptosis." (PMID 30451832, 2018). "Our immunoblotting results suggest that polydatin stimulates autophagy-related proteins, including phosphorylated ULK1, BECN1, ATG5, and LC3B, and has a protective effect against colon cancer." (PMID 34573109, 2021). "Clinical studies have shown that a lack of autophagy-related proteins such as LC-3II, ATG5, and Beclin 1 can indicate poor prognosis in colon cancer patients." (PMID 38650627, 2024). "Reciprocally, abolition of AIF/EndoG-dependent apoptosis by AIF- or EndoG-siRNA enhanced Atg5 and Atg7 expression induced by FK-16, indicating that inhibition of AIF/EndoG-dependent apoptosis magnified the autophagic signal in FK-16-treated colon cancer cells." (PMID 23700428, 2013).
colon carcinoma (continued). "We also measured the expression of the two autophagy upregulating proteins Beclin1 and Atg-5 in SW-480 and HCT-116 colon cancer cells, but itraconazole had no detectable effects on their expression." (PMID 32681018, 2020). "The result showed that the Livin-H2A.XY142ph axis could directly target ATG5 and ATG7 in colon cancer cells under starvation, while Livin-H2A.XY142F axis had no combination with ATG5/ATG7 in colon cancer cells under starvation." (PMID 31799193, 2019).
liver fibrosis (22 papers, 2018 to 2025). "It was also shown that Atg5-deficient macrophages facilitate chemically-induced liver fibrosis through stimulating myofibroblasts (likely to be activated HSCs) to express fibrogenic genes." (PMID 29999454, 2018). "Autophagy-related gene 5 (ATG5) is a pivotal protein in the assembly of the autophagosome; myeloid-specific deletion of ATG5 leads to increased ROS production and enhanced inflammatory cell recruitment associated with exacerbated liver injury in CCl4-induced murine liver fibrosis." (PMID 41479922, 2025). "Thus, there is still a substantial gap between the current understanding of the potential roles of autophagy deficiency in the progression of liver fibrosis and whether Atg5 and Atg7 can be used as effective targets for the treatment of liver diseases." (PMID 32724454, 2020). "Autophagy also inhibits fibrosis, as it has been reported that autophagy-mediated miR-30a-5p/ATG5 axis can alleviate liver fibrosis through induced apoptosis suppression." (PMID 41035887, 2025). "In recent years, a series of studies have focused on the role of ATG-5 in the development of liver fibrosis." (PMID 40430125, 2025). "In the mouse liver fibrosis experiment, ATG5, RB1CC1, and PARK2 were at higher levels in HF group than those in HC group." (PMID 38481992, 2024). "Ni and colleagues showed that in hepatocyte-specific ATG5-knockout mice, hepatic fibrosis was exacerbated." (PMID 38086792, 2023). "Previous studies have shown that liver-specific atg5 knockout mice display hepatic fibrosis alongside the increased transcription of TGF-β target genes such as CTGF, collagen, and α-SMA." (PMID 36078110, 2022). "In contrast, silencing Atg5 in the liver during preneoplastic stage facilitated liver fibrosis and tumorigenesis." (PMID 31695131, 2019). "Reports suggesting that ATG-5 could be used as a therapeutic target in the treatment of liver fibrosis are mostly based on studies conducted in mice or cell cultures." (PMID 40430125, 2025). "Consistently, the curative effect of EGCG on liver fibrosis was reversed by leupeptin and si-ATG5 treatment, as evidenced by the increased protein expression level of fibrosis-related gene α-SMA and increased collagen deposition in the liver tissues of rcccDNA mice." (PMID 37122751, 2023). "Therefore, selective inhibition of autophagy in hepatic stellate cells using, e.g., Atg5/7 knockdown seems to be a promising experimental strategy to counteract liver fibrosis in aged livers." (PMID 33628363, 2021). "In contrast, some herbal monomers have been shown to alleviate liver fibrosis by upregulating ATG5, and overexpression of ATG5 could promote drug-induced inhibition of hepatic stellate cell activation and liver fibrosis, which corresponds to the results of our bioinformatics analysis." (PMID 38481992, 2024). "In addition, ATG5 expression was elevated after liver fibrosis was alleviated." (PMID 35194023, 2022). "In addition to impacts on liver fibrosis, impaired macrophage autophagy by Atg5 deletion could promote proinflammatory macrophage polarization and enhance the immune response in obese mice." (PMID 31614437, 2019). "Macrophage-specific deletion of Atg5 could aggravate CCL4-induced liver fibrosis." (PMID 31614437, 2019). "Blocking autophagy in hematopoietic stem cells using 3-methyladenine, doxazosin or specific siRNA targeting ATG5 and ATG7 resulted in reduced activation of HSCs and attenuation of liver fibrosis." (PMID 40406118, 2025). "When autophagy in HSCs was blocked with 3-methyladenine or specific siRNAs against ATG5 and ATG7, HSCs activation was reduced, and hepatic fibrosis was alleviated." (PMID 38086792, 2023). "Briefly, lncRNA SNHG1 silencing was observed to downregulate SMURF1 by upregulating miR-15a, diminishing ubiquitination of UVRAG to activate ATG5/Wnt5a axis, which accelerated HLC differentiation from BMSCs and repressed liver fibrosis to inhibit cirrhosis." (PMID 35194023, 2022).
liver fibrosis (continued). "TGF-β1 significantly increased the protein of autophagy and liver fibrosis, including LC3BII, ATG5, α-SMA, and Col.I; Sal B inhibits JS1 autophagy and activation by inhibiting the formation of autophagosomes and autophagic flux." (PMID 35991894, 2022). "BBR downregulated ATG5 and ATG7 expression with a decrease in α-SMA in HSCs, which is consistent with the double IF staining in mouse liver fibrosis." (PMID 34864819, 2021). "In particular, atg5 deletion and genetic inhibition of LAP components in the myeloid compartment exacerbate hepatic inflammation in mice with chronic liver injury, thus enhancing liver fibrosis." (PMID 34459017, 2021). "Moreover, the protein expression of ATG5 and LC3 II/I, as well as the data of transmission electron microscopy (TEM), showed that autophagy was activated in liver sinusoidal endothelium in human liver fibrosis." (PMID 29760379, 2018). "Moreover, we confirmed the involvement of ATG5, PARK2, and RB1CC1 in HF in a mouse liver fibrosis model, among which RB1CC1 was never before reported in liver fibrosis." (PMID 38481992, 2024).
ovarian carcinoma (22 papers, 2015 to 2026). A malignant neoplasm originating from the surface ovarian epithelium. "Finally, we explored whether factors such as ATF4, GPX4, GSS, KEAP1, NFE2 like BZIP transcription factor 2 (NEF2L2), SLC7A11, SQSTM1, ATG3, ATG4D, and ATG5 have potential as non-invasive diagnostic markers for ovarian cancer." (PMID 37215446, 2023). "As transmission electron microscopy (TEM) shown, the number of autophagosomes increased following pyrimethamine treatment, and this was accompanied by a dose-dependent elevation in autophagy marker expression (LC3-II, ATG5) in ovarian cancer cells." (PMID 40918465, 2025). "Pyrimethamine treatment induced the expression of autophagic biomarkers (LC3-II, ATG5) in ovarian cancer cells in a dose-dependent manner." (PMID 40918465, 2025). "For example, BHS synergistically interacted with cisplatin to chemosensitise ovarian cancer by suppressing autophagy via downregulating the HIF‐1α/ATG5 axis." (PMID 39051750, 2024). "For example, BHS inhibited cisplatin resistance in ovarian cancer by suppressing autophagy via downregulating the HIF‐1α/ATG5 axis." (PMID 39051750, 2024). "The results of cDNA expression profile analysis indicated that six genes, including GPX4, GSS, KEAP1, SQSTM1, SLC7A11, ATG3, and ATG5, were highly expressed in tumor tissues from patients with ovarian cancer." (PMID 37215446, 2023). "ATG5 remains unchanged while other genes show lower levels in quiescent sorted cells, and knockdown of ATG5 induces the ovarian cancer cells arrested in G0/G." (PMID 30319732, 2018). "Autophagy is critical for quiescent ovarian cancer spheroid cells to reenter the cell cycle because rapamycin can promote quiescent ovarian cancer spheroid cells to form colonies on soft agar and knockdown of ATG5 can arrest ovarian cancer cells in G0/G1." (PMID 30319732, 2018). "Inhibition of autophagy by knockdown of ATG5 abolishes the self-renewal ability of ovarian cancer spheroid cells." (PMID 30319732, 2018). "Inhibition of autophagy by knockdown of ATG5 prevents ovarian cancer spheroid cells with stem cell-like properties to enter quiescent state." (PMID 30319732, 2018). "In the arsenic trioxide-treated ovarian cancer cells, Atg5 knockdown reduced autophagy via altering the ratio of LC3-II/LC3-I, which is an indicator of the autophagic progress." (PMID 28545442, 2017). "Knockdown of ATG5 decreases ROS and rescues ovarian cancer cells from necrotic death after ARHI re-expression." (PMID 26247722, 2015). "Taken together, these findings suggest that there is a correlation between the magnitude of the early effector response and overall in vivo efficacy, and underscore the therapeutic potential of ATG5 deletion as a strategy to improve CAR-T outcomes in ovarian cancer." (PMID 41279553, 2025). "For example, circEEF2 could bind with miR-6881-3p to upregulate ATG7 and ATG5 expression, promoting the autophagy process in ovarian cancer." (PMID 36187468, 2022). "Knockdown of ATG5 prevents ovarian cancer spheroid cells to enter quiescent state." (PMID 30319732, 2018). "Knockdown of ATG5 dramatically impaired the ability of A2780 spheroid cells to form colonies on soft agar, indicating that autophagy is required for the self-renewal of ovarian cancer spheroid cells." (PMID 30319732, 2018). "CYLD did not influence the expression levels of RIP3 (necrosis marker), p62 and ATG5 (autophagy marker), as well as levels of GPX4 and SLC7A11 (ferroptosis marker) in ovarian cancer A2780 and OVCAR3 cell lines." (PMID 40012003, 2025). "Under the same conditions, autophagosome proteins such as BECN1, p-ULK1, ATG5, and LC3B were induced by β-sitosterol in the examined ovarian cancer cells." (PMID 34679718, 2021). "Pharmacologic inhibition with the autophagy inhibitor chloroquine or genetic ablation with CRISPR/Cas9 knockout for the autophagy essential gene ATG5 significantly reduced the CSC property and chemoresistance of ovarian cancer cells." (PMID 30477228, 2018).
ovarian carcinoma (continued). "Up-regulation of miR-30d contributes to ovarian cancer development by suppressing Beclin1, BNIP3L, ATG12, ATG5, ATG2 directly and inhibiting LC3-I conversion to LC3-II." (PMID 27825125, 2016). "In ovarian cancer, the oncomiR miR-30d was illustrated to impair autophagy by suppressing a multitude of autophagy-related genes including Beclin1, BNIP3L, ATG12, ATG5, ATG2 directly and inhibiting LC3-I conversion to LC3-II." (PMID 27825125, 2016). "Taken together, our results suggest that deletion of ATG5 metabolically primes CAR-T cells for enhanced cytotoxicity in immune-suppressive conditions, thereby improving the therapeutic potential of αFR CAR-T cells for ovarian cancer immunotherapy." (PMID 41279553, 2025). "The results of multiple gene correlation analyses indicated that there was a significant linear relationship (positive correlation) between the expression of ATF4 in ovarian cancer tissue and the expression levels of GPX4, GSS, KEAP1, NFE2L2, SLC7A11, ATG3, ATG4D, and ATG5." (PMID 37215446, 2023). "However, in ovarian cancer, ginsenoside 20(S)-Rg3 enhanced autophagy by upregulating autophagy-related molecules, including LC3-II, Atg5 and Atg7, thereby inhibiting the invasion and metastasis of ovarian cancer cells." (PMID 32934709, 2020). "Knockdown of ATG5 enhanced ROS production which can be reduced by ROS scavenger N-acetyl cysteine (NAC) in A2780 cells, indicating that autophagy can induce antioxidant response in ovarian cancer cells." (PMID 30319732, 2018). "Down-regulation of ATG5 and ATG7 block autophagy induction in ovarian cancer cell lines." (PMID 27825125, 2016). "Furthermore, study suggested that resveratrol could induce human ovarian cancer cells (OVCAR-3 and Caov-3) apoptosis by triggering ATG5 expression and promoting LC3 cleavage, inhibiting autophagy with chloroquine reduced resveratrol-induced cells death." (PMID 27825125, 2016). "To further support the data that QC-induced ovarian cancer cell death is dependent on autophagy, we performed FACS analysis on C13 non-targeted control transduced (NTC) and ATG5 knockdown (KD) cells after treatment with QC ± caspase inhibitor (Z-VAD-FMK)." (PMID 33919392, 2021). "Unlike the Beclin1, efficient ATG5 and ATG7 knockdown could block autophagy induction in ovarian cancer cell lines, as evidenced by suppression of LC3-II." (PMID 27825125, 2016).
liver cancer (21 papers, 2017 to 2025). An epithelial or non-epithelial malignant neoplasm that arises from the liver. "At the same time, many studies in genetically engineered mice have confirmed that the deletion of the At96/Beclinl allele of autophagy regulatory gene induces liver cancer, and the deletion of Atg5 or Atg7 can also cause liver cancer in mice." (PMID 37038623, 2023). "According to Li's group, WTAP promotes ATG5 mRNA translation in liver cancer ferroptosis by up‐regulating ATG5 post‐transcriptionally in a manner that is m6A–YTHDC2 dependent." (PMID 39135292, 2024). "Studies have revealed that endoplasmic reticulum stress can inhibit the expression of autophagy‐related genes, including ATG12 and ATG5, allowing liver cancer cells to evade autophagic degradation and enhance their capacity for growth and proliferation." (PMID 37728036, 2023). "To investigate the relationship between autophagy and DNA damage, we first inhibited autophagy in HepG2 liver cancer cells by inhibiting the autophagy related Atg5 gene using two different shRNA-Atg5 lentivirus sequences." (PMID 34031266, 2021). "Additionally, NaHS upregulates the expression of autophagy-related proteins, specifically microtubule-associated protein light chain 3-II (LC3-II) and autophagy-related protein 5 (Atg5), inhibiting division, proliferation, and migration of liver cancer cells." (PMID 40923024, 2025). "The compound does not cause apoptotic death in liver cancer cell lines; instead, it induces cell death through autophagy, as evidenced by increased levels of ATG5, ATG7, beclin, and BNIP, and the induction of the LC3-I to LC3-II conversion." (PMID 39275166, 2024). "One study showed that ATG5 could also induce macrophage-mediated autophagy in liver cancer, and ATG5 inhibition prevents macrophage-mediated autophagy and restores oxaliplatin sensitivity." (PMID 35814435, 2022). "To test more directly whether TAZ is degraded by autophagy, we first deleted ATG7 or ATG5 expression in the liver cancer cell lines HLE and Huh7 using the CRISPR-Cas9–mediated gene disruption system." (PMID 34088666, 2021). "Given that SH3BGRL could inhibit cell proliferation of liver cancer cells in starvation and the documentation of the interaction of SH3BGRL with ATG5, we tentatively checked whether SH3BGRL involves in the autophagy of liver cancer cells, as ATG5 plays a crucial role in autophagy." (PMID 37138798, 2023). "Therefore, we concluded that SH3BGRL may interact with ATG5 to prevent its ubiquitination-related degradation to enhance the consequent autophagy of liver cancer cells." (PMID 37138798, 2023). "SMAD2 and SMAD3 correlated with autophagy-related scores (based on ATG12, ATG7, ATG3, ATG5, ATG4B, PIK3C3, PRKAA2, and GABARAPL1) in liver cancer." (PMID 37790613, 2023). "Moreover, mice lacking Atg5 or Atg7 have been reported to develop liver cancers." (PMID 35054896, 2022). "In mice with knockout of core autophagy proteins, ATG5 and ATG7, the absence of these proteins leads to autophagy-defective hepatocytes that develop liver cancer due to mitochondrial damage and oxidative stress." (PMID 39349421, 2024). "Statistical analysis indicated that SH3BGRL is correlated to ATG5 expression level, but not ATG12 level in liver cancers." (PMID 37138798, 2023).